MMP10 (matrix metallopeptidase 10)
Diseases named in the same sentence as MMP10 in open-access papers (continued):
Sharing a sentence is not in itself a finding about the gene and the disease.
endometrial cancer (2 papers, 2025). Primary or metastatic malignant neoplasm involving the endometrium (mucous membrane that lines the endometrial cavity). "We investigated the levels of MMP-7, MMP-26, MMP-3, and MMP-10 in comparison with the levels of a tumor marker (CA125) in the plasma of postmenopausal patients in early stages of endometrial cancer (EC) compared with control groups: patients with benign lesions (myoma uteri) and healthy controls." (PMID 40332487, 2025).
focal and segmental glomerulosclerosis (2 papers, 2022 to 2025). "Furthermore, co-localization of MMP-10 and β-catenin was validated in tubular epithelia of human kidney biopsies from patients with DN, IgAN, membranous nephropathy (MN) and focal and segmental glomerulosclerosis (FSGS)." (PMID 40382334, 2025). "MMP-10 can also be detected in the glomerular podocytes of CKD patients with diabetic kidney disease (DKD), IgA nephropathy (IgAN), and focal segmental glomerulosclerosis (FSGS)." (PMID 35216251, 2022).
glaucoma (2 papers, 2014 to 2015). Increased pressure in the eyeball due to obstruction of the outflow of aqueous humor. "Expression of proteins enriched in the vitreous (CCL2, IGFBP2, MMP10, HGF, TNFRSF11B (OPG)) was localized by immunohistochemistry in eyes of patients with severe ischemic CRVO followed by secondary glaucoma." (PMID 25978399, 2015).
heart failure (2 papers, 2024 to 2025). Inability of the heart to pump blood at an adequate rate to meet tissue metabolic requirements. "On the contrary, elevated MMP-10 is associated with cardiovascular disease (CVD), promoting inflammation, plaque formation, and heart failure progression." (PMID 41301428, 2025). "Elevated MMP-10 levels reflect the myocardium's need to regulate extracellular matrix dynamics in heart failure." (PMID 39726944, 2024). "Reverse Mendelian randomization suggested that the onset of heart failure might potentially influence the levels of four inflammatory factors, with ARTN and FGF5 decreasing after the onset of heart failure, and SLAM and MMP-10 increasing." (PMID 39726944, 2024). "Moreover, reverse Mendelian randomization analysis identified inflammatory factors such as ARTN, FGF5, MMP-10, and SLAM, whose increased secretion may represent an adaptive response to heart failure." (PMID 39726944, 2024).
kidney stone (2 papers, 2024 to 2025). "The analysis revealed an AUC value of 0.724 for KLK1 and 0.737 for MMP10, highlighting their substantial diagnostic value in evaluating kidney stone progression." (PMID 39606015, 2024). "Through machine learning algorithms, KLK1 and MMP10 were identified as optimal feature genes, significantly upregulated in kidney stone samples, with high diagnostic value." (PMID 39606015, 2024). "The results showed that the AUC (area under the curve) values of KLK1 and MMP10 were 0.724 and 0.737, respectively, both exceeding 0.7, indicating their high diagnostic value in evaluating the progression of kidney stones." (PMID 39606015, 2024). "KLK1 and MMP10 were identified as potential diagnostic markers and key players in kidney stone progression." (PMID 39606015, 2024). "In the subsequent integration of machine learning algorithms, we identified two optimal feature genes—KLK1 and MMP10, and confirmed their significant upregulation in kidney stone samples." (PMID 39606015, 2024). "The results indicated a significant upregulation of KLK1 and MMP10 genes in kidney stone samples, suggesting their pivotal roles in kidney stone progression (p < 0.01)." (PMID 39606015, 2024). "Given the potential importance of KLK1 and MMP10 in kidney stones, we further conducted gene set enrichment analysis (GSEA)." (PMID 39606015, 2024). "The expression levels of the two optimal feature genes, KLK1 and MMP10, were validated in 29 kidney stone samples and 33 normal samples." (PMID 39606015, 2024).
muscular disease (2 papers, 2021 to 2023). Myopathy is a peripheral nervous system disease consisting of any abnormal condition or disease of the muscular tissues; commonly designates a disorder involving skeletal muscle. "To investigate the role of MMP-10 in severe muscular disease, we analyzed the consequences of MMP-10 ablation in hearts from aged mdx mice." (PMID 34947929, 2021).
myocardial infarction (2 papers, 2023 to 2025). Gross necrosis of the myocardium, as a result of interruption of the blood supply to the area, as in coronary thrombosis. "Importantly, a study on mice suggests that production of MMP-10 increases in the heart following myocardial infarction." (PMID 40343765, 2025). "Colchicine reduced mRNA and protein expression of MMP2 in vitro, mitigated mRNA expression of MMP-3, MMP-9, and MMP-10 in aortas of mice and abolished the relative mRNA expression of MMP-9 in infarct area of myocardium after myocardial infarction in mice." (PMID 38001470, 2023).
oral squamous cell carcinoma (2 papers, 2023 to 2025). "MMP1 and MMP10 are expressed in oral squamous cell carcinoma (OSCC) tissues and are considered prognostic indicators." (PMID 40001606, 2025). "From the table, MMP1 and MMP10 were highly expressed in oral squamous cell carcinoma." (PMID 36941602, 2023).
prostate tumor (2 papers, 2017 to 2022). "Additionally, MMP-10 expression was significantly increased in shBAT1 mice prostate tumors when compared to control." (PMID 36505884, 2022). "IHC analysis showed that shBAT1 mice prostate tumors increased TNF-α, IL-6, and MMP-10 expression." (PMID 36505884, 2022).
pulmonary arterial hypertension (2 papers, 2022 to 2023). Pulmonary arterial hypertension (PAH) is a group of diseases characterized by mean pulmonary artery pressure >20 mmHg and elevated pulmonary arterial resistance leading to right heart failure. "M1 macrophages could release MMP10 to induce pulmonary artery smooth muscle cells proliferation and migration, further leading to vascular remodeling and pulmonary arterial hypertension." (PMID 37006258, 2023).
skin cancer (2 papers, 2001 to 2023). "Our results show that MMP-10 expression does not correlate with the invasive behaviour of tumours as assessed by their histology and MT1-MMP expression, but may be induced by the wound healing and inflammatory matrix remodelling events associated with skin tumours." (PMID 11237387, 2001).
squamous cell carcinoma (2 papers, 2001 to 2012). A carcinoma arising from squamous epithelial cells. "In addition, inhibition of p38 and ERK in a squamous cell carcinoma cell line SCL-1 has been shown to inhibit UV-A and UV-B-induced matrix metalloproteinases MMP-1 (stromelysin-2) and MMP-10 (interstitial collagenase) expression both in vitro and in vivo." (PMID 22312244, 2012).
systemic lupus erythematosus (2 papers, 2022 to 2024). An autoimmune multi-organ disease typically associated with vasculopathy and autoantibody production. "In addition, serum MMP-10 levels exhibit the capacity to distinguish systemic lupus erythematosus (SLE) from healthy controls, which predicts organ damage and lupus nephritis in SLE patients." (PMID 35216251, 2022).
ulcerative colitis (2 papers, 2015 to 2025). An inflammatory bowel disease involving the mucosal surface of the large intestine and rectum. "Mmp3, Mmp10, and Mmp13 mRNA levels were significantly upregulated in ulcerative colitis and colorectal adenocarcinoma compared with the levels of normal cohorts." (PMID 25742789, 2015). "Three of four hub genes identified as NF-κB-regulated in active ulcerative colitis were also regulated in PC-3 MCS in our study (CXCL1, MMP1, and MMP10)." (PMID 40001606, 2025).
viral infections (2 papers, 2021 to 2023). "MMP-2 is generally considered protective for the airways, however MMP-10 is induced by viral infections and is linked to increased submucosal thickness." (PMID 33718297, 2021).
Alport syndrome (1 paper, 2022). A rare renal disease characterized by glomerular nephropathy with hematuria progressing to end-stage renal disease (ESRD), frequently associated with sensorineural deafness, and occasionally with ocular anomalies. "In the light of recent studies, it is conceivable that FAK is a potent regulator for MMP-10 expression, at least in Alport syndrome." (PMID 35216251, 2022). "It has been shown that MMP-10 is upregulated as early as 3-weeks in FVB/N CD151-/- mice, suggesting an underlying function of MMP-10 in the early stage of Alport syndrome." (PMID 35216251, 2022).
aortic aneurysm (1 paper, 2022). A ruptured aneurysm located in the wall of the proximal portion of the descending aorta proceeding from the arch of the aorta. "MMP10 overexpression has been described as compromising vascular integrity and to be associated with aortic aneurysms and atherosclerotic lesions." (PMID 35884862, 2022).
aortic valve calcification (1 paper, 2024). "Likewise, plasma levels of MMP-10 correlate with neurological damage and mortality in patients with cerebrovascular disease and with aortic valve calcification." (PMID 39456453, 2024).
benign breast tumor (1 paper, 2020). "Plasma levels of MMP-10 were significantly elevated in patients with BC as compared with the healthy group and the benign breast tumor group (p < 0.001)." (PMID 33371324, 2020). "Moreover, median levels of MMP-10 in all stages of BC were significantly increased as compared with healthy and benign breast tumor subjects (p < 0.001)." (PMID 33371324, 2020).
Blindness (1 paper, 2015). Blindness is the condition of lacking visual perception defined as a profound reduction in visual perception. "Ocular localization of the proteins that showed significantly higher expression in the vitreous than in blood (CCL2, IGFBP2, MMP10, HGF, TNFRSF11B) was investigated in histological specimens of eyes from patients with painful blindness due to secondary glaucoma after CRVO." (PMID 25978399, 2015).
brain injuries (1 paper, 2022). "A study of traumatic brain injuries suggest MMP-1 and perhaps MMP-10 to be involved in breakdown of BBB and edema formation; however, this warrants further investigation." (PMID 36248130, 2022).
breast tumors (1 paper, 2016). "Although MMP10 has been less studied compared to other MMPs, its expression has been shown in human specimens of luminal A breast tumors." (PMID 27351228, 2016). "Similarly, MMP10 levels are elevated in luminal breast tumors compared to their normal counterparts (p = 2.2e–16)." (PMID 27351228, 2016).
cardiomyopathy (1 paper, 2021). A disease of the heart muscle or myocardium proper. "Ablation of a specific MMP can lead to compensatory effects, thus we next examined expression of Mmp3, which belongs to the stromelysin family, as well as examining MMP-10, Mmp2 and Mmp9, the two major MMP gelatinases that have been associated with DMD cardiomyopathy." (PMID 34947929, 2021).
carpal tunnel syndrome (1 paper, 2020). Entrapment of the median nerve in the wrist that is characterized by numbness, tingling and painful movement. "DNA variants located within MMP1 (rs1799750), MMP3 (rs3025058, rs679620, rs591058, rs650108), MMP10 (rs486055), and MMP12 (rs2276109), have independently and/or in combination been associated with Achilles tendinopathy (AT) risk, Carpal Tunnel Syndrome (CTS) and ACL ruptures." (PMID 32650441, 2020).
cerebral infarction (1 paper, 2022). An ischemic condition of the brain, producing a persistent focal neurological deficit in the area of distribution of the cerebral arteries. "However, Zhu has observed that MMP10 rs17435959 and rs17293607 are independent of susceptibility to atherothrombotic cerebral infarction in Zhejiang Han population." (PMID 36282475, 2022).
Cerebral ischemia (1 paper, 2011). Restriction of arterial blood supply to the brain associated with insufficient oxygenation to support the metabolic requirements of the tissue. "The expression of MMPs, especially MMP2, MMP9 and MMP10, is induced by cerebral ischemia." (PMID 21541054, 2011).
cerebral microbleeds (1 paper, 2022). Cerebral microbleeds are a group of pathological processes affecting the small arteries, arterioles, capillaries and venules of the brain, as detected by brain imaging techniques. "They found an increase in CSF levels of MMP-10 coupled with a decrease in TIMPs in participants with AD and concurrent cerebral microbleeds." (PMID 36031900, 2022).
cholangiocarcinoma (1 paper, 2025). A carcinoma that arises from the intrahepatic biliary tree (intrahepatic cholangiocarcinoma) or from the junction, or adjacent to the junction, of the right and left hepatic ducts (hilar cholangiocarcinoma). "HGF upregulates the phosphorylation of FOS-like 1 (FOSL1) within cholangiocarcinoma cells, promoting the expression of matrix metallopeptidase 10 (MMP10), and consequently enhancing the invasive and migratory abilities of cholangiocarcinoma cells." (PMID 41048570, 2025).
clear cell adenocarcinoma (1 paper, 2016). A malignant neoplasm composed of glandular epithelial clear cells. "In grouping of histological subtypes, clear cell adenocarcinomas showed a significantly higher MMP10 expression rates (44.6% vs 18.2%; p = 0.002)." (PMID 27072580, 2016).
complication (1 paper, 2015). Any disease or disorder that occurs during the course of, or because of, another disease, treatment, or procedure. "Levels of HbA1c, LDL, triglycerides, MMP-1, MMP-2, MMP-3, MMP-9, MMP-10, TIMP-1 and markers of LGI and ED were significantly higher in individuals with vascular complications compared to those without." (PMID 25848912, 2015).
Crohn disease (1 paper, 2023). A gastrointestinal disorder characterized by chronic inflammation involving all layers of the intestinal wall, noncaseating granulomas affecting the intestinal wall and regional lymph nodes, and transmural fibrosis. "MMP-3 and MMP-10 are the main enzymes indicating the development of Crohn’s disease." (PMID 37895400, 2023).
cutaneous melanoma (1 paper, 2018). A primary melanoma arising from atypical melanocytes in the skin. "In cutaneous melanoma, MMP10 is potentially modified by modification of histone acetylation." (PMID 29933410, 2018).
cyst (1 paper, 2024). A sac-like closed membranous structure that may be empty or contain fluid or amorphous material. "MMP-10, involved in ECM degradation and inflammatory regulation, could disrupt the ECM environment within ovarian follicles, impair ovarian angiogenesis, and potentially lead to cyst formation—a hallmark of PCOS." (PMID 39691364, 2024).
cystic fibrosis (1 paper, 2022). Autosomal recessive disorder caused by pathogenic variants in the CFTR gene (cystic fibrosis transmembrane conductance regulator), which encodes a chloride and bicarbonate channel expressed in epithelial cells, and follow the diagnosis criteria. "Reportedly, MMP-10 is expressed by macrophages in the human lung of patients with cystic fibrosis." (PMID 34975336, 2022).
dilated cardiomyopathy (1 paper, 2024). Cardiomyopathy which is characterized by dilation and contractile dysfunction of the left and right ventricles. "Conversely, in the low MMP10 expression subgroup, pathways significantly enriched included adolescent-onset type diabetes, linoleic acid metabolism, drug metabolism-cytochrome P450, protein digestion and absorption, and dilated cardiomyopathy." (PMID 39606015, 2024).
Duchenne muscular dystrophy (1 paper, 2023). Duchenne muscular dystrophy (DMD) is a neuromuscular disease characterized by rapidly progressive muscle weakness and wasting due to degeneration of skeletal, smooth and cardiac muscle. "Most importantly, MMP-10 conserves its protective effect in the satellite cell-derived myoblasts isolated from a Duchenne muscular dystrophy patient by decreasing the accumulation of damaged DNA." (PMID 37228645, 2023).
dysplasia (1 paper, 2025). A usually neoplastic transformation of the cell, associated with altered architectural tissue patterns. "In our study we tried to assess the potential of MMP-3, MMP-7, MMP-10, and MMP-26, which showed significant differences in concentrations between the groups of healthy women, dysplasia patients, and cancer patients, and also demonstrated the ability to distinguish benign from malignant lesions." (PMID 41462922, 2025).
endometrioid ovarian cancer (1 paper, 2025). "We are currently the first research laboratory group to demonstrate the diagnostic utility of MMP-10 in endometrioid ovarian cancer." (PMID 41007705, 2025). "In the case of MMP-26, similarly to MMP-10, higher levels of this enzyme were found in patients with ovarian cysts (10,985 pg/mL) compared to patients with endometrioid ovarian cancer (9425 pg/mL) and healthy women (7163 pg/mL)." (PMID 41007705, 2025).
frontotemporal dementia (1 paper, 2022). Frontotemporal dementia (FTD) comprises a group of neurodegenerative disorders, characterized by progressive changes in behavior, executive dysfunction and language impairment, as a result of degeneration of the medial prefrontal and frontoinsular cortices. "At the level of individual markers, multiple studies have shown that MMP-10 levels are increased in AD and frontotemporal dementia (FTD) CSF compared to healthy controls." (PMID 36031900, 2022).
glomerulonephritis (1 paper, 2017). A renal disorder characterized by damage in the glomeruli. "Elevation of MMP10 was already reported in SLE patients and in a murine LN model with glomerulonephritis." (PMID 29026368, 2017).
Helicobacter infection (1 paper, 2025). "MMP10, which has a significant correlation with CagA-positive Helicobacter infection, can control cytokine-associated chemotaxis, which causes leukocytes to migrate to the infected site and aids in the evolution of inflammation." (PMID 40264171, 2025).
hematoma (1 paper, 2018). A hematoma is a collection of blood from a vascular structure into an extravascular space. "MMP 10 at an early timepoint (within 2 days of ICH ictus) was the only variable significantly associated with hematoma expansion (p = 0.03) and MMP 3 at timepoint 1 was the only variable significantly associated with END (p = 0.05)." (PMID 30258397, 2018).
interstitial cystitis (1 paper, 2025). A rare chronic debilitating urogenital disease characterized by urinary frequency, urgency, and pelvic pain. "There is no existing literature that clarifies the relationship between CCL18, MMP10, and WIF1 with interstitial cystitis." (PMID 40435311, 2025).
ischemia reperfusion injury (1 paper, 2025). Adverse functional, metabolic, or structural changes in ischemic tissues resulting from the restoration of blood flow to the tissue (reperfusion), including swelling; hemorrhage; necrosis; and damage from free radicals. "Comparable induction of MMP-10 expression and activity was observed after unilateral ischemia-reperfusion injury (UIRI)." (PMID 40382334, 2025).
kidney cancer (1 paper, 2022). Primary or metastatic malignant neoplasm involving the kidney. "We compared two of them—MMP-3 (stromelysin-1) and MMP-10 (stromelysin-1)—in human kidney cancer with the parts of the same organ that were unaffected." (PMID 36231910, 2022).
kidney tumor (1 paper, 2022). "Our results show that MMP-10 is about three times more active in healthy human kidney than MMP-3 and four times more active in both grades of kidney tumor in comparison to healthy tissue." (PMID 36231910, 2022).
Kyphosis (1 paper, 2021). Exaggerated anterior convexity of the thoracic vertebral column. "After noticing first signs of physical discomfort, such as slack posture, lack of mobility, abnormal field behavior and marked kyphosis, most aged MMP-10-deficient mdx mice were humanely sacrificed to avoid pain and suffering." (PMID 34947929, 2021).